TNF (tumor necrosis factor)
Diseases named in the same sentence as TNF in open-access papers (continued):
Sharing a sentence is not in itself a finding about the gene and the disease.
Insulin resistance (continued). "Notable proinflammatory agents that directly affect signaling pathways related to insulin resistance, dyslipidemia, and/or vascular dysfunction/hypertension include tumor necrosis factor-α (TNF-α), interleukin-6 (IL-6), interleukin-1β (IL-1β), and monocyte chemoattractant protein-1 (MCP-1)." (PMID 35887592, 2022). "Increased concentrations of TNF-α have been shown to induce insulin resistance by increasing phosphorylation of the insulin signaling pathway in animal and cell models, although the administration of anti-TNF-α mAbs had little effect in patients with type 2 diabetes." (PMID 36548717, 2022). "Administration of TNF-α to experimental animals induced insulin resistance." (PMID 35807921, 2022). "In addition, anti-inflammatory drugs targeting TNF-α, IL-1β, and NF-kB improved insulin resistance and fasting blood glucose levels in clinical studies." (PMID 36145139, 2022). "IL-6 is a marker of the MetS, but TNF-alpha is involved in insulin resistance and dyslipidemia." (PMID 35053667, 2022). "However, factors that lead to insulin resistance, such as TNFα, fatty acids, Cblb, and Crebbp, inhibit the IRS-1 down-regulation." (PMID 36353510, 2022). "Furthermore, the treatment of T2DM mice with MEP resulted in reduced endotoxemia and insulin resistance-related pro-inflammatory cytokines interleukin 1β (IL-1β), tumor necrosis factor-alpha (TNF-α), and interleukin 6 (IL-6)." (PMID 36276816, 2022). "Not only increased PGRN levels in blood correlated positively with body mass index (BMI), fat mass, fasting glucose and insulin levels, and insulin resistance, but also mediated TNF-a-induced insulin resistance through the regulation of IL-6 expression in 3T3-L1 adipocytes." (PMID 35419363, 2022). "In addition, we demonstrated that ALA decreases levels of proinflammatory TNF-α but also increases the synthesis of anti-inflammatory IL-10 in the hypothalamus of insulin-resistant rats." (PMID 35391928, 2022). "An integrated system pharmacology analysis then revealed that various targets such as PPARG, RELA, EGFR and numerous pathways such as TNF signalling, PI3K-Akt signalling, MAPK signalling and NF-κB signalling were involved in the underlying mechanisms of GQD in improving diabetic insulin resistance." (PMID 36187136, 2022). "Previously it was reported that IL-6, especially TNF-α, may have an important role in the etiology of diabetes and insulin resistance, and IL-6 levels may increase 2–3 times." (PMID 34174798, 2022). "Specific oral taxa could contribute to redirecting consumption of energy by facilitating insulin resistance through increasing levels of TNFα and lipo-polysaccharides or reducing levels of adiponectin." (PMID 35906254, 2022). "In these studies, increased inflammatory modifications were observed in adipose tissue from obese rodents and humans, and enhanced secretion of pro-inflammatory cytokine tumor necrosis factor-α(TNF-α) was able to induce insulin resistance by inactivating insulin receptor substrate 1 (IRS-1)." (PMID 36012516, 2022). "Chronic toxoplasmosis was suggested to play a role in the pathogenesis of type 2 diabetes mellitus (T2D) due to the correlation between the state of insulin resistance in T2D and the elevated levels of circulating inflammatory cytokines including IL-2,4; IL-6,5; IL-12,6; TNF; and IFN." (PMID 36672526, 2022). "In addition, previous studies found that resistin was weakly correlated with other inflammatory molecules such as TNF-α, IL-6, insulin, and insulin resistance measured by homeostasis model assessment-insulin resistance (HOMA-IR)." (PMID 36428592, 2022). "Moreover, EBRT significantly decreased serum levels of insulin (p = 0.035), TNF-α (p = 0.046), hsCRP (p = 0.037), and insulin resistance (p = 0.045) as well as body fat percentage (p = 0.023)." (PMID 36207735, 2022).
Insulin resistance (continued). "Furthermore, TNF‐α‐mediated inflammatory signalling pathways impair insulin receptor signal transduction, resulting in insulin resistance, which is crucial for NAFLD progression." (PMID 35713152, 2022). "Furthermore, inhibition of TNF-α decreased the excretion of urinary albumin, partially indicating the mitigation of insulin resistance." (PMID 35855831, 2022). "Through network pharmacology analysis, our study revealed that HGD might take part in the treatment of DN through pathways associated with insulin resistance, PI3K-Akt, toll-like receptors, MAPK, and TNF." (PMID 34035828, 2021). "Previous studies showed that lean subjects with insulin resistance have an unfavorable inflammatory profile with elevated tumor necrosis factor-α and interleukin-6, while obese subjects exhibited a comparable inflammatory status regardless of insulin resistance." (PMID 33478525, 2021). "Moreover MH-76 reduced abdominal adiposity and insulin resistance, as well as decreased TNF-α concentration and lipid peroxidation in adipose tissue." (PMID 34069933, 2021). "Additionally, HF and HF+FO/D groups showed insulin resistance, adipocyte hypertrophy, increased lipolysis and secretion of TNF-α, resistin and IL-10 adipokines by ING and RP adipocytes, and adiponectin only by the HF+FO/D group in ING adipocytes." (PMID 33652751, 2021). "Periodontitis‐related systemic inflammation may contribute to insulin resistance through elevated blood levels of adipocytokines, such as tumor necrosis factor alpha, IL‐6, and leptin, which inhibit the insulin receptor and its downstream signaling." (PMID 34463983, 2021). "The decreased phosphorylation level of JNK suggests that KRAS may inhibit adiponectin expression by regulating JNK and TNF-α, thereby inhibiting adipogenesis under physiological conditions and affecting adipogenesis by regulating insulin resistance." (PMID 34948427, 2021). "We also demonstrated that subdiaphragmatic vagus nerve amputation eliminated the beneficial effects of exercise training on splenic TNF-α levels, acetylcholine concentration, and ChAT activity and prevented exercise from improving insulin resistance in HFD mice." (PMID 34717724, 2021). "For example, TNF-α can ultimately lead to insulin resistance, reducing insulin sensitivity." (PMID 34836432, 2021). "Additionally, TNFα has roles in metabolism, such as insulin resistance and lipid metabolism as well as skeletal growth." (PMID 34831397, 2021). "Taken together, our findings suggested that the uptake of H-Exo by liver macrophages may result in macrophage activation and subsequent release of TNF-α and IL-6, thus contributing to the development of insulin resistance." (PMID 33431899, 2021). "IL-6 seems to induce insulin resistance and an increased production of CRP in the liver and TNF-α may also induce insulin resistance by suppressing the expression of the insulin-sensitive glucose transporter in peripheral tissues." (PMID 34650454, 2021). "Additionally, the positive correlations found between alterations in atherogenicity and insulin resistance markers and TNF-α concentration (ng/L) in the serum were among the interesting findings of the current analysis." (PMID 34742318, 2021). "TNF-α in particular plays a vital role in insulin resistance and tissue inflammation." (PMID 33628374, 2021). "Moreover, health improvement was linked to two established mediators of insulin resistance: TXNIP and TNFα." (PMID 34371884, 2021). "Furthermore, TNF-α is correlated to insulin resistance, this molecule (TNF-α) and ROS can activate the transcription factor of NF-κB, which leads to the induction of genes responsible for carcinogenesis, cell proliferation and apoptosis." (PMID 34535145, 2021).
Insulin resistance (continued). "In particular, tumor necrosis factor alpha plays a major role in hepatic insulin resistance, and it inactivates the insulin receptor substrate by serine phosphorylation through activation of a serine/threonine kinase, thus blocking the insulin receptor signaling cascade." (PMID 34463983, 2021). "Finally, inhibition of inositol receptor pathways by IL-6 and TNF-α leads to decreased glucose transport, thus resulting in insulin resistance." (PMID 33716966, 2021). "Also, increased levels of TNF-α and IL-6 along with other proinflammatory cytokines were found in obese children and adolescents with insulin resistance and/or T2DM." (PMID 34344352, 2021). "Moreover, ATM-derived TNFα is suggested to be the leading promoter of adipose-specific insulin resistance through various mechanisms." (PMID 33897419, 2021). "Consistently, elevation of systemic inflammatory responses in relation to sleep restriction was also well demonstrated, and proinflammatory cytokines such as tumor necrosis factor and C-reactive protein were released and subsequently promoted insulin resistance." (PMID 34556157, 2021). "Similarly, in humans, TNF-α, as a pro-inflammatory cytokine, is engaged in the pathogenesis of several metabolic diseases, mainly chronic, such as diabetes, contributing to insulin resistance and disturbed fatty acid metabolism." (PMID 34316205, 2021). "Such insulin resistance was associated with modest, not statistically significantly higher expression of canonical markers of low-grade inflammation, namely IL-6 and TNFα, in adipose tissue and liver." (PMID 33819308, 2021). "The elevated TNF levels were previously found to be relevant to insulin resistance and T2DM." (PMID 35010205, 2021). "Increased TNF-α concentrations might induce insulin resistance via changes in the adipocyte insulin signaling pathway, as suggested in one study." (PMID 33954196, 2021). "Furthermore, TNF-α and IL-6 concentrations are generally related to insulin levels; in fact, these cytokines play an important role in the pathogenesis of insulin resistance." (PMID 33530512, 2021). "TNF-α plays an essential role, in creating a linkage among insulin resistance." (PMID 33918576, 2021). "In this study, we observed that PU supplementation remarkably decreased gut microbiota disturbance-induced release of TNF-α and IL-1β, thus inhibiting the IKKβ/NF-κB inflammatory pathway phosphorylation and reducing the production of TNF-α and IL-1β, thereby improving insulin resistance." (PMID 34262422, 2021). "TNF-α levels are positively correlated with other markers of insulin resistance." (PMID 33800490, 2021). "In addition, osteoporosis and sarcopenia shared common underlying mechanisms, including insulin resistance, decreased anabolic hormones, such as IGF-1 and testosterone, increased inflammatory cytokines, including IL-1, IL-6, and TNF-α, as well as dysbiosis." (PMID 33807573, 2021). "Furthermore, a positive correlation was found between miRNA-122 expression and TNF-α (r = 0.82), IL-6 (r = 0.83) and insulin resistance (r = 0.8)." (PMID 34077450, 2021). "Decreasing insulin resistance, reduction of some inflammatory cytokines like IL-6 and TNF-α, modulation of angiotensin-converting enzyme 2 (ACE2) receptor, and improving neutrophil to lymphocyte ratio are some of the potential mechanisms of metformin in COVID-19 patients with DM." (PMID 33815295, 2021). "Furthermore, IL-1β and MCP-1 produced by TNF-α-stimulated mouse adipocytes/monocytes were shown to induce insulin resistance in the liver and adipose tissues." (PMID 33859296, 2021). "In addition, studies on ethanol-fed mice proved that alcohol determines macrophage infiltration, cytokine releasing of TNF alpha and Interleukine 6, and insulin resistance in adipose tissue." (PMID 35027961, 2021).
Insulin resistance (continued). "TNFα disrupts the insulin signaling pathway by disrupting such phosphorylation events, specifically by inhibiting the phosphorylation of IR substrate 1, leading to a subsequent decreased glucose uptake, and eventual insulin resistance." (PMID 34576943, 2021). "Additionally, it can regulate the gut microbiota, increase IL-10, and reduce IL-6 and tumor necrosis factor-α (TNF-α), as well as liver injury, and further reduce insulin resistance and regulate lipid metabolism disorders." (PMID 34574191, 2021). "It shows that the level of TNF-α is affected by the vagus nerve to regulate the nerve-related anti-inflammatory activity in the spleen, which can help improve glucose intolerance and insulin resistance through exercise." (PMID 34717724, 2021). "Moreover, by increasing lipolysis, TNFα increases the release of free fatty acids (FFAs) which influence glucose metabolism and induce insulin resistance." (PMID 34068151, 2021). "Therefore, in burns, aside from being a proinflammatory cytokine, TNFα contributes to insulin resistance and increases the level of blood glucose and of FFAs, which are indicators of a hypermetabolic state." (PMID 34068151, 2021). "Moreover, TNF-α can lead to insulin resistance related to obesity, which has a significant role in atherosclerosis." (PMID 34572503, 2021). "The mechanism mainly involves pathways relative to insulin resistance, TNF-α, and apoptosis." (PMID 33505505, 2021). "In addition, TNFα induces insulin resistance through serine phosphorylation of IRS-1, with consequent impairment of normal insulin signaling." (PMID 33805912, 2021). "It is well established that adipocyte-derived adipo-, cyto- and/or chemokines, such as leptin, adiponectin, tumour necrosis factor-alpha (TNF-α), interleukins (ILs), and macrophage chemoattractant protein, are involved in the onset and progression of insulin resistance and NAFLD." (PMID 33794740, 2021). "Interestingly, a correlation between mitochondrial dysfunction, insulin resistance, and high tumor necrosis factor-α (TNF-α) levels suggests that progressive mitochondrial impairment determines the development of hepatic inflammation." (PMID 34202179, 2021). "In addition, high levels of endotoxemia have been shown to increase levels of TNF-α, IL-6, and insulin resistance." (PMID 34073366, 2021). "3T3-L1 cells were treated with TNFα as a model of inflammation-induced insulin resistance in vitro." (PMID 34650665, 2021). "Similarly, as a crucial proinflammatory mediator, tumour necrosis factor (TNF) induces insulin resistance by impairing insulin signalling through serine phosphorylation." (PMID 34675276, 2021). "On the other hand, increased IL-6 and TNF-α serum levels represent the insulin resistance state." (PMID 34572503, 2021). "TXNIP is a mediator of insulin resistance in liver, skeletal muscle and adipose tissue, and impaired pancreatic beta-cell insulin secretion and TNFα decreases insulin receptor signaling in adipose tissue and skeletal muscle, particularly prior to development of T2DM." (PMID 34371884, 2021). "Therefore, the current community-based study tests the interactions between the apM1 genotypes, TNF-α genotypes, and insulin resistance on the occurrence of Taiwanese MetS." (PMID 33997011, 2021). "In addition, TNF-α increases circulating levels of leptin and resistin when interacting synergistically with IL-6, favoring increased peripheral insulin resistance and greater chances of developing T2DM." (PMID 33520042, 2021).
Insulin resistance (continued). "The reversal of insulin resistance induced by tRES-HESP was related inversely to expression of TNFα and TXNIP and may reflect countering of MG accumulation and protein glycation, with consequent decreased activation of the UPR." (PMID 34371884, 2021). "Furthermore, ablation of TIMP-3 and subsequent dysregulated ADAM17 activity and TNF release promoted insulin resistance and hepatosteatosis." (PMID 33579029, 2021). "Combined exenatide and metformin showed better effects on female than male patients for improving insulin sensitivity and serum lipid profile, reducing insulin resistance, increasing adiponectin levels, and decreasing the levels of HbA1c, BMI, resistin, TNF-alpha, CRP (p<0.05)." (PMID 34367059, 2021). "Intermittent hypoxia could lead to glucose intolerance and insulin resistance by promoting the release of pro-inflammatory cytokines, such as interleukin-6 and tumor necrosis factor." (PMID 34393806, 2021). "However, tumor necrosis factor-α (TNF-α), involved in insulin resistance, stimulates CDK5 phosphorylation in an ERK-dependent manner." (PMID 34069890, 2021). "Increased PAI-1 and TNF-α levels induce the development of thrombosis and insulin resistance." (PMID 33584134, 2021). "Additionally, oxidative stress induces insulin resistance of adipocytes and increases secretion of several cytokines and pro-inflammatory interleukins, IL-6 and TNF-α by adipocytes." (PMID 34439481, 2021). "When considering the preliminary evidence of clinical efficacy of carnosine in T2DM patients on insulin resistance, AGEs, and TNF-α, future clinical studies should be conducted in T2DM patients with MCI to better understand the therapeutic potential of carnosine against cognitive decline." (PMID 33806459, 2021). "TNF-α may induce insulin resistance by directly affecting target organs (e.g., liver, muscle, and adipocytes) and by indirectly promoting the production of free fatty acids from adipocytes." (PMID 34203460, 2021). "High IL-10 levels may also increase insulin sensitivity by ameliorating the inflammatory responses to TNF-α and IL-6, which contribute to insulin resistance in PCOS." (PMID 34233746, 2021). "TNF plays a crucial role in insulin resistance and the onset of T2D." (PMID 35821991, 2021). "The levels of TNFα increased proportionally to adiposity and insulin resistance." (PMID 33807712, 2021). "Under obesogenic conditions, hypertrophic adipocytes begin to secrete TNF-α, which in turn induces the expression of an array of adipokines able to attract circulating monocytes to the adipose depots, thus further fueling and worsening insulin resistance." (PMID 34680177, 2021). "Moreover, IL-1β contributes to the expression of tumor necrosis factor alpha (TNFα), which also promotes insulin resistance." (PMID 33546399, 2021). "TNF-α is a mediator of insulin resistance through blocking the action of insulin." (PMID 34712684, 2021). "Arterial hypertension, dyslipidemia, older age, sedentary lifestyle, and abdominal obesity are key risk factors for T2DM since the adipose tissue secretes several biomarkers, such as resistin, TNF-α, and IL-6, which can induce a chronic inflammatory state and insulin resistance." (PMID 34012421, 2021). "Reduction of insulin resistance through PAR-γ/GLUT4-leptin/TNF-α signaling pathway." (PMID 34299610, 2021). "More specifically, the secretion of TNF-α from the synovial or extra-articular infiltrates might be an important mediator of insulin resistance, as it hampers downstream insulin signaling and by inhibiting adiponectin release." (PMID 34579044, 2021). "Moreover, macrophage and Kupffer cell infiltration contribute to the progression of NAFLD and insulin resistance secreting pro-inflammatory cytokines such as TNF-α, IL-6 and IL-1β." (PMID 34684533, 2021). "TNFα may also play a critical role in insulin resistance, specifically by downregulation of GLUT-4 and IRS-1." (PMID 34949179, 2021).